NF1 (neurofibromin 1)
Diseases named in the same sentence as NF1 in open-access papers (continued):
Sharing a sentence is not in itself a finding about the gene and the disease.
melanoma (continued). "BRAF, NRAS, or NF1 mutations can co-occur with C/T mutations in the promoter region of the telomerase reverse transcriptase (TERT) gene, which are frequently observed in melanoma, occurring in 30–85% of cases depending on disease stage." (PMID 39859576, 2025). "Patients with NF1-mutant melanoma tend to be older at diagnosis and predominantly male." (PMID 40867277, 2025). "Consequently, preclinical studies that evaluate treatment strategies against other melanoma subtypes – such as those with mutant NRAS, NF1 loss, or triple wild-type have yet to be tested in this context." (PMID 40944916, 2025). "In contrast, high-CSD melanomas frequently lack BRAF V600E mutations but may have alterations in genes such as NRAS, NF1, and KIT while exhibiting a higher TMB." (PMID 40125165, 2025). "Hence, all available evidence points to Nf1 haploinsufficiency stimulating intradermal melanoma tumorigenesis." (PMID 39804140, 2025). "In addition, if the total intradermal melanoma burden per mouse in volume is summed up, all Nf1flox/+ mice exhibited equivalent or greater volumes than all Nf1 +/+ mice, because most of the Nf1flox/+ mice had more than one simultaneous intradermal melanoma." (PMID 39804140, 2025). "NF1 co-mutations with either BRAF or NRAS, as well as frequently with other melanoma-associated oncogenes, suggest that this is overall a weaker oncogenic driver that may cooperate with additional MAPK pathway alterations to drive melanomagenesis." (PMID 38611025, 2024). "Additionally, 2, 4, and 1 NF1-mutant melanomas harbored chromothripsis events spanning BRAF, NRAS, and NF1, respectively." (PMID 38758740, 2024). "Loss of NF1 function co-occurres also with the mutated BRAF and NRAS melanomas." (PMID 39340537, 2024). "Here, we report a rare case of melanoma developing in an existing cNF in an individual with NF1." (PMID 39687068, 2024). "Acral melanomas display a profile of driver mutations similar to that observed in cutaneous melanomas, with BRAF being the most frequently mutated, followed by NRAS and NF1 mutations." (PMID 39727691, 2024). "Additionally, tumors with NF1 loss share a pan-cancer RAS pathway activation RNA signature with tumors that have mutations in RAS family genes, including melanomas with BRAF mutations." (PMID 39016685, 2024). "However, ongoing basket clinical trials are investigating targeted therapy in NF1 mutant solid tumors, including melanomas." (PMID 38534309, 2024). "We report a rare case of malignant melanoma developing in a pre-existing cNF in a patient with NF1." (PMID 39687068, 2024). "While cases with BRAF TCGA driver mutations alone were consistent with previously reported data suggesting a predominance of class I mutations in BRAF mutant melanoma, only one of eleven BRAF co-mutated cases (co-occurring with either NRAS or NF1) exhibited a class I BRAF mutation." (PMID 38611025, 2024). "All but one BA-SV affecting NF1 in acral and mucosal melanomas were deletion events." (PMID 38758740, 2024). "Instead, high-CSD melanoma is characterized by a more miscellaneous set of MAPK pathway mutations, such as BRAF V600K, NRAS, or KIT mutations, or inactivation of the negative regulators of Ras, NF1, or RASA2." (PMID 38247727, 2024). "Given that a higher TMB has been correlated with response to ICI, both in our study and in several others, and TMB in NF1 mutant melanomas is generally very high, further investigation is warranted as to why NF1 mutation alone did not correlate with improved ICI response." (PMID 38611025, 2024). "However, NF1-mutant melanomas had significantly higher numbers of DEL events per tumor compared with the other genomic subtypes (Wilcoxon-Mann-Whitney, FDR P < 0.033)." (PMID 38758740, 2024).
melanoma (continued). "Genomic classification based on the pattern of the most prevalent significantly mutated genes identified four distinct subtypes of melanoma, including mutant BRAF (n = 114), mutant RAS (mainly NRAS, n = 81), mutant NF1(n = 23), and Triple-WT (wild-type, n = 36)." (PMID 38082384, 2023). "In addition, knockout of PRKAA2 in NF1-mutant melanoma cells increased their growth as xenografts in immunodeficient mice, and increased the presence of metastases in brain when they were administered by intracardiac injection." (PMID 37962491, 2023). "While this study was in progress, Zheng's group showed that knockout of PRKAA2 in NF1-mutant melanoma cells promoted anchorage-independent growth in soft agar, while ectopic expression of PRKAA2 in NF1- and AMPK-α2-deficient human melanoma cells greatly reduced this." (PMID 37962491, 2023). "However, dysregulated RAS, due to either RAS mutation itself or neurofibromin 1 (NF1) deletion/mutation, is the typical cause of RAS activation in BRAF class III melanomas." (PMID 37760573, 2023). "Our data showed that cotargeting PEX3 and UGCG could (a) sensitize RAS-mutant and NF1-mutant melanoma cells to MEKi-induced apoptosis, (b) delay the onset of acquired resistance in vivo, and (c) restore drug sensitivity in resistant/relapsed melanomas." (PMID 37616051, 2023). "Thus, this study explored a potential universal efficacy of RSK inhibitors in malignant melanoma with MAPK pathway hyperactivation – including RAS- and NF-1-mutated in addition to BRAF-mutated melanomas." (PMID 37464364, 2023). "Furthermore, pharmacological inhibition was tested in tumors developed from cell lines obtained from a genetically engineered melanoma model that reflects human triple wild-type (BRAF/RAF/NF1-WT) melanoma and its response to immunotherapy." (PMID 37712416, 2023). "In addition to BRAF, other genes have been found mutated in sporadic melanomas including NRAS, TERT, NF1, and KIT." (PMID 37627054, 2023). "Finally, knockout of PRKAA2 in NF1-mutant melanoma cells increased their growth as xenografts in immunodeficient mice, and increased the presence of metastases in brain when they were administered by intracardiac injection." (PMID 37962491, 2023). "The non-overlapping mutations in BRAF, NRAS, and NF1 are sometimes referred to as “driver” mutations, due to their ability to independently promote growth, proliferation, and survival of melanoma cells." (PMID 37444637, 2023). "Another sample showed coexisting NRAS and NF1 mutations, supporting the three-group melanoma classification (BRAF-mutant, RAS-mutant, non-BRAF-mutant/non-NRAS-mutant)." (PMID 36901733, 2023). "Analyzing NF1 mutation status has some prognostic value even though there are no target therapies for NF1-mutated melanomas, but such cases respond favorably to immunotherapy." (PMID 37958863, 2023). "The most important mutated genes contributing to melanoma development comprise BRAF, NRAS, and NF1, all of which may upregulate the MAPK/ERK pathway and promote cell proliferation." (PMID 36143375, 2022). "Moreover, this expression appeared constitutive and independent of the tumor mutational status, as it was observed in all cell lines tested that presented the most common melanoma-associated mutations, namely BRAF/V600E, NRAS/Q61K and NF1." (PMID 35428910, 2022). "Genetically, melanoma has been classified based on driver mutations activating the MAPK signaling pathway as (I) BRAF-mutant (50–60%), (II) RAS-mutant (20–30%), (III) NF1-mutant (10–15%) or (IV) triple (BRAF, NRAS and NF1) wild-type melanoma (~10%)." (PMID 36077603, 2022). "These subtypes are represented by BRAF mutant melanomas, which account for approximately 50% of melanomas; NRAS-, KRAS-, and HRAS-mutant melanomas, which are about 25%; NF1-mutant melanomas (15% of melanomas); and triple-wild-type melanomas, which account for the remaining 10% of cases." (PMID 35563772, 2022).
melanoma (continued). "Melanomas most often harbor mutations that affect the Ser/Thr kinase BRAF (50%), the small GTPase NRAS (25%), or the negative regulator of RAS, neurofibromin 1 (NF1) (14%), resulting in increased RAS/mitogen-activated protein kinase (MAPK) signaling." (PMID 36309522, 2022). "Promising preclinical data suggest that strategies combining MAPK and PI3K inhibitors may similarly prove beneficial in NRAS- and NF1-driven melanoma." (PMID 35234863, 2022). "Though NF1 mutations ordinarily happen in CMs lacking mutations in BRAF or NRAS, nearly 4% of melanomas with mutations in BRAF or NRAS also exhibit NF1 mutations." (PMID 36143375, 2022). "The third major oncogenic lesion in melanoma affects the tumor suppressor NF1." (PMID 35234863, 2022). "It has been observed that NF1 inactivating mutations occur in melanomas without BRAF and NRAS mutations and cause the activation of the MAPK pathway." (PMID 36614156, 2022). "NF1 loss often happens in melanomas lacking mutations in BRAF or NRAS, although in 4% of CM these three mutations can coexist." (PMID 36143375, 2022). "Neurofibromin 1 (NF1), a tumour suppressor gene encoding a negative regulator of RAS, is the most frequently mutated gene in sun-exposed malignant melanoma, after BRAF and NRAS, being associated with a high risk of metastasis and a high rate of treatment failure." (PMID 35334544, 2022). "Little is known about the response of NF1-driven melanoma to targeted therapies." (PMID 35234863, 2022). "Because of the invasive properties of the primary nf1/pten-mutant melanomas, we also tested the feasibility of their intramuscular transplantation into rag2−/− zebrafish, where the tumor cells not only expanded within muscle, but also invaded neighboring tissues such as the ventral fin." (PMID 34331013, 2021). "Thus, there is a clear need for effective small-molecule inhibitors to overcome the aggressive growth properties of NF1/PTEN-mutant melanoma." (PMID 34331013, 2021). "Similarly, the expression levels of these genes were comparable in BRAF-, NRAS-, and NF1-mutant, as well as triple wild-type melanoma tumors indicating that the presence of mRNAs in qCLASH hybrids is not influenced by stage of disease or mutational background." (PMID 33806450, 2021). "In addition, mutation of functional NF1 is associated with BRAFi resistance in melanoma and mutations in the PTPN11, SOS1, RAF1 and SPRED1 genes frequently co-occur with NF1 loss." (PMID 33807778, 2021). "Finally, an approach involving the stabilization of the NF1 protein by reducing its degradation has been suggested to enhance sensitivity to trametinib in melanoma cell lines." (PMID 34831002, 2021). "The frequency of NF1 mutations in melanomas is approximately 15%, with a higher frequency observed in older patients, chronic sun damage lesions, desmoplastic melanomas, and BRAF/NRAS wild-type melanomas (a frequency of 70%)." (PMID 34831002, 2021). "The NF1-mutant category refers to cases lacking either BRAF or RAS mutations, whereas NF1 mutations can also arise as a mechanism of resistance to RAF/MEK-targeted therapies in BRAF-mutated melanoma." (PMID 34331013, 2021).
melanoma (continued). "The most prevalent significantly mutated genes in melanoma such as BRAF, NRAS, KRAS, HRAS, and NF1 were also explored; the results indicated that the high-FRGs score group have lower mutation frequencies in NRAS, KRAS, and NF1 compared to the low-FRGs score group." (PMID 34745259, 2021). "Nevertheless, although 15% of sporadic melanoma bear NF1 somatic mutations, no targeted treatment has been developed for this patient’s subgroup, mainly due to the complexity of the protein." (PMID 34362135, 2021). "Hence, combined activation of the RAS and PI3K pathways, a high proliferative rate, and the lack of apoptosis likely account for the rapid onset and high growth rate of nf1/pten-mutant melanomas." (PMID 34331013, 2021). "These animals develop spontaneous malignant peripheral nerve sheath tumors (MPNSTs) with low penetrance, but not melanomas, beginning at the age of 1.5 years, indicating that nf1-loss alone is not sufficient to drive melanomagenesis." (PMID 34331013, 2021). "Homozygous deletion of NF1 was identified in melanoma cell lines." (PMID 34680938, 2021). "In primary melanoma patient biopsies, NF1 mutations were not correlated with hot-spot BRAF mutations, a finding consistent with a redundant role for these two types of mutations in activating RAS-MAPK signaling." (PMID 34331013, 2021). "These melanomas rarely harbor BRAF, NRAS, or NF1 mutations (triple wild-type)." (PMID 34571969, 2021). "Thus, these two pathways appear to function redundantly in driving the proliferation of nf1/pten-mutant melanomas." (PMID 34331013, 2021). "Furthermore, the MEK inhibitor trametinib attenuated MEK phosphorylation and exhibited greater potency than another MEK inhibitor, PD0325901, in NF1-null melanoma cells." (PMID 34063141, 2021). "Somatic mutations in genes encoding protein actors of this phosphorylation cascade constitutively activate the MAPK pathway: mutations in BRAF, neurofibromin 1 (NF1), NRAS, and c-KIT are the most frequent, representing 50, 20, 20, and 2% of melanomas, respectively." (PMID 33804655, 2021). "Notably, the three-drug combination identified in our NF1/PTEN-mutant melanoma model also showed anti-melanoma activity in BRAF-mutant melanoma cells harboring PTEN-mutation." (PMID 34331013, 2021). "However, in melanomas harboring both BRAF and NF1 mutations, it is more likely that tumors can escape from MAPK inhibiting therapy." (PMID 34350118, 2021). "The isobologram summarizes the combination index (CI) at the IC50 when the SMO inhibitor MRT-92 and the BRD4-degrader MZ1 were combined, showing a moderate synergistic anti-proliferative effect (CI < 1) in melanoma cells independently of their BRAF, NRAS, and NF1 mutational status." (PMID 33958721, 2021). "However, we found pathological mutations in the PTPN11, NF1, CUX1, IKZF1 gene and TERT promoter, which better fit a diagnosis of a melanoma than of lung cancer." (PMID 34819052, 2021). "Given its greater efficiency and lower costs compared to murine models, our zebrafish experimental system appears ideal for pursuing additional classes of pathway inhibitors in NF1/PTEN-mutant melanomas, as single agents and in combination, to define their clinical translational potential." (PMID 34331013, 2021). "Polymerase Chain Reaction (PCR) and Sanger sequencing techniques were performed to identify the mutational status of BRAF, NRAS, KRAS, NF1, KIT, PDGFRA and SF3B1 on 19 melanomas of the female genital tract, paired with 25 cutaneous melanomas, 18 acral melanomas and 11 melanomas of nasal cavity." (PMID 34102999, 2021). "Indeed, when we combined 7.5 μM venetoclax and 2.5 μM S63845 with 10 μM sirolimus, we observed greatly enhanced growth suppression of nf1/pten-mutant melanoma cells." (PMID 34331013, 2021). "However, we observed a significant higher ST8SIA1 expression in melanoma patients with BRAF V600e mutation compared to those that were triple WT (wild type of BRAF, NRAS, and NF1 mutations) or NRAS mutation(s) alone." (PMID 32358995, 2020).
melanoma (continued). "Even though solar ultraviolet exposure is the main environmental risk factor for cutaneous melanoma development, there are still genetic susceptibility factors, such as germline mutations in p16 or CDK4, and genesis of melanoma, such as the main genetic drivers BRAF, NF1 and NRAS mutations." (PMID 32333246, 2020). "Because melanoma patients commonly harbor genetic alterations in BRAF, NRAS, CDKN2A, or NF1 genes that contribute to tumor progression, we examined potential associations between these genetic alterations and IRAK-M levels in melanoma cell lines and patient samples." (PMID 32533049, 2020). "It should be noted that NF1, a common DNA mutation in melanoma, is not included in the standard Illumina panel and was therefore not evaluated." (PMID 31857724, 2020). "As NF1 deficiency mediated escape from BRAF-driven OIS and BRAF inhibitor resistance in melanoma, which could be combatted with MEK inhibitors, we hypothesize NF1 loss may be a key targetable mechanism of resistance to PI3K/AKT/mTORC1 inhibitors." (PMID 31285545, 2020). "In contrast, CDKN2A promoter hypermethylation occurs most frequently in NRAS-mutant melanoma (87.7%) and is less common in melanoma with BRAF mutations (67.0% with CDKN2A promoter methylation) and in melanomas with NF1 mutations (77.3% showing CDKN2A promoter methylation)." (PMID 33076392, 2020). "Each of these variants of uncertain significance occurred in BRAF, NRAS, or NF1 mutant melanomas." (PMID 32483240, 2020). "Melanoma cell growth is typically driven by the ERK/MAPK pathway, which is hyper‐activated in at least 80% of melanomas that occur through mutations in NRAS (~20%), BRAF (~50%) and NF1 (~14%)." (PMID 31323160, 2020). "Interestingly, their expressions were independent of the status of key melanoma mutations, including BRAF, neurofibromin 1 (NF1), and RAS mutations and triple wild type in melanoma." (PMID 33014847, 2020). "The most common somatic mutations are activating point mutations in the v-Raf murine sarcoma viral oncogene homolog (BRAF; 35–50% of melanomas) and neuroblastoma RAS viral oncogene homolog (NRAS; 10–25%), as well as loss-of-function mutations affecting neurofibromin 1 (NF1; ~15%)." (PMID 31470659, 2019). "Moreover, multiple studies have linked NF1 activity to RAS and ERK activity, including its role in therapy resistance upon targeted inhibition of the MAPK pathway in melanoma and lung cancer." (PMID 30858928, 2019). "In other tumor types, such as melanoma, colorectal, and lung cancer, activating BRAF mutations occur mostly in a non-overlapping distribution with other genes that converge on activation of ERK signaling pathways (i.e., KRAS, NRAS, NF1, EGFR)." (PMID 31158244, 2019). "Interestingly, mutations in NF1 were observed at 14 different loci, with primarily truncating effects, which is consistent with the knowledge that NF1 serves as a tumor suppressor in melanoma." (PMID 30820351, 2019). "Major genetic drivers of melanoma oncogenesis are the gain-of-function mutations of B-Raf (BRAF), neurofibromin 1 (NF1), and NRAS, which contribute to the activation of the ERK/MAPK pathway, resulting in the uncontrolled growth, proliferation, and enhanced survival of tumor cells." (PMID 31426515, 2019).